KRAS (KRas proto-oncogene, GTPase)
Diseases named in the same sentence as KRAS in open-access papers (continued):
Sharing a sentence is not in itself a finding about the gene and the disease.
thyroid nodule (14 papers, 2015 to 2026). A small circumscribed mass in the THYROID GLAND that can be of neoplastic growth or non-neoplastic abnormality. "BRAF mutational analysis followed by N, H, and KRAS codon 61 mutational analysis in indeterminate thyroid nodules would streamline the management of patients with malignancies, mostly FVPTC." (PMID 25648502, 2015). "Mutations in RAS proto-oncogenes (NRAS, HRAS, KRAS) are common in thyroid nodules, though their prognostic significance remains unclear." (PMID 41784850, 2026). "The RAS genes family (NRAS, HRAS, and KRAS) mutations represent the majority (about 70%) of all mutated cases, especially in indeterminate cytology, and they can be seen in histologically benign and malignant thyroid nodules." (PMID 38884926, 2024). "In indeterminate thyroid nodules, NRAS mutations are typically the most frequent, followed by KRAS and HRAS." (PMID 40748901, 2025). "In one unique case of a female, different multiple mutations were found in her three thyroid nodules: CCDC6/RET + NRAS Q61R in the first nodule, CCDC6/RET + KRAS G13D in the second nodule, and NRAS Q61R + PTEN Q245* in the third nodule." (PMID 37882481, 2023). "In a study that demonstrated the variety in the molecular profile of 96 surgically resected thyroid nodules, RAS (HRAS, NRAS, KRAS) oncogene mutations were present, either alone or with other mutations in almost one-half of cases (46 of 96 cases; 48%)." (PMID 37175943, 2023). "Other features such as gender, multifocality, thyroiditis, presence of thyroid nodules, and mutation status of KRAS, BRAF, and TERT did not significantly differ between the high- and low-risk groups in this validation set." (PMID 40650680, 2025). "Furthermore, molecular analysis using the following markers (BRAF V600E, NRAS, HRAS, KRAS, RET/PTC, and PAX8/PPARg) to evaluate preoperative genetic mutations and rearrangements has been shown to have significant diagnostic value in thyroid nodules with indeterminate cytology." (PMID 37732121, 2023).
tubular adenoma (14 papers, 2006 to 2024). A usually polypoid neoplasm arising from the glandular epithelium. "This patient (number 63) had a KRAS-mutated 4 cm tubular adenoma with low-grade dysplasia and KRAS-mutated ctDNA was identified in his plasma." (PMID 32517177, 2020). "KRAS missense mutations were found in carcinomas (3 out of 8; mutation frequency = 37.5%), in villous adenomas (5 out of 10; mutation frequency = 50%) and in tubular adenomas (2 out of 9; mutation frequency = 22.2%)." (PMID 39021676, 2024). "We assayed a TMA containing 25 duplicate FFPE colon samples (normal mucosa, tubular adenomas, serrated adenomas, primary tumors, and matched metastases) of unknown KRAS mutation status for KRAS codon 12 and 13 mutations." (PMID 24280411, 2013). "Only two of 259 tubular adenomas (0.8%) harboured a KRAS mutation." (PMID 21457162, 2011). "Loss of expression of MGMT correlated with KRAS mutation in small tubular adenomas (P < 0.04)." (PMID 16879389, 2006). "Among them, Villous adenomas presented higher frequencies of KRAS mutations and MSI compared to the tubular adenomas." (PMID 33087131, 2020). "In the low grade intraepithelial neoplasias with mutant KRAS, 46(46/123,37.4%)were tubulovillous adenomas, 24(24/155,15.5%) were tubular adenomas, 12(12/52,23.1%)were serrated adenomas, and 3(3/7,42.9%) were villous adenomas." (PMID 26910894, 2016). "Interestingly, a mutation of KRAS gene at codon 146 was observed at tubular adenoma with moderate atypia of nodular part, however, there was not any mutation examined in tubular adenoma with mild atypia of flat part." (PMID 23957258, 2013). "No KRAS or RNF43 variants were detected among the four lesions, including tubular adenomas." (PMID 36419139, 2022).
chronic myelomonocytic leukemia (13 papers, 2018 to 2025). A myelodysplastic/myeloproliferative neoplasm which is characterized by persistent monocytosis, absence of a Philadelphia chromosome and BCR/ABL fusion gene, fewer than 20 percent blasts in the bone marrow and blood, myelodysplasia, and absence of PDGFRA or PDGFRB rearrangement. "In dieser Studie verglichen wir die Ergebnisse von Patienten mit KRAS-Mutation der nationalen „Austrian Biodatabase for chronic myelomonocytic leukemia“ (ABCMML) mit Patienten der internationalen Plattform cBioPortal." (PMID 40694264, 2025). "In this study we compared findings in KRAS-mutated patients of the Austrian biodatabase for chronic myelomonocytic leukemia (ABCMML) with that from the CMML cohort documented in cBioPortal." (PMID 40694264, 2025). "In 2 patients (patient 19 with ECD/chronic myelomonocytic leukemia and patient 37 with B-ALL/HS), identical NRAS/KRAS mutations were identified in both neoplasms, suggesting a clonal relationship." (PMID 40453055, 2024).
COVID-19 (13 papers, 2020 to 2024). A disease caused by infection with severe acute respiratory syndrome coronavirus 2. "The pathway analysis of WB samples from patients with COVID-19 compared with HC showed notable enrichment of genes in multiple pathways associated with “inflammatory response”, “interferon-alpha”, “G2M checkpoint”, “mitotic spindle”, and “interferon-gamma response” as well as “KRAS Signaling Up”." (PMID 35922752, 2022). "MAIT cells showed enrichment for TNF signaling and KRAS across COVID-19 groups and γδ T cells for cell cycle pathways." (PMID 35216673, 2022). "Exposure to CS or nicotine upregulated many genes within AGE-RAGE signalling with high confidence, including CCND1, CXCL8, HRAS, IL6, KRAS and TNF, suggesting that smokers have a hyperactive AGE-RAGE and are therefore more at risk of severe COVID-19." (PMID 38991709, 2024). "KRAS and RAC1 encode for GTPase and are respectively downregulated and upregulated in AD+COVID-19." (PMID 34948400, 2021). "Interestingly, primary cilia house a number of oncogenic molecules including smoothened, KRAS, epidermal growth factor receptor, and platelet-derived growth factor receptor, and thus, the role in the immune response to COVID-19 would need further investigation." (PMID 33437935, 2021). "However, whether KRAS is involved in the development of inflammatory cardiomyopathy in patients recovering from COVID-19 and what role it plays in this process have not been published." (PMID 37457560, 2023).
Familial adenomatous polyposis (13 papers, 2016 to 2025). Familial adenomatous polyposis (FAP) is characterized by the development of hundreds to thousands of adenomas in the rectum and colon during the second decade of life. "BRAF p.V600E (50%) or KRAS (p.G12V/D, 40%) mutations were present in 90% of HPs, with one other HP carrying APC p.R213* (rs587781392) which has been reported in the ClinVar database to be associated with familial adenomatous polyposis and APC-associated cancers." (PMID 40757636, 2025).
intestinal cancer (13 papers, 2015 to 2025). "Cross-talk between the WNT and MAPK signaling pathways has been documented due to APC loss and KRAS mutation in intestinal cancer." (PMID 34830178, 2021). "KRas is frequently mutated in lung and intestinal cancers and both exhibit higher than average KRas4A expression with KRas4A also contributing a higher share of total KRas expression in intestine." (PMID 28117393, 2017). "In addition, KRAS mutations are the main intestinal cancer markers." (PMID 35975176, 2022). "This allows sustained proliferation of epithelial PDAC cells and thus tumour progression independent of overt EMT induction and contrasts with WNT- and KRAS-driven intestinal cancer subtypes, which are refractory towards aberrantly expressed SNAIL." (PMID 36882420, 2023). "To test the hypothesis that SNAIL cooperates specifically with KRAS, but not WNT pathway activation, to induce cancer progression across tumour entities, we activated SNAIL in vivo in a KRASG12D-driven model of serrated intestinal cancer." (PMID 36882420, 2023).
angiosarcoma (12 papers, 2006 to 2025). A malignant tumor arising from the endothelial cells of the blood vessels. "Mutations in KRAS have been found in 13–60% of angiosarcomas as well, leading to activation of both the PI3K/mTOR and MAPK pathways." (PMID 29872503, 2018). "A recent deep sequencing study investigated mutations in the RAS/MAPK pathway comprehensively and found that 53% of angiosarcomas contained hotspot mutations in KRAS, HRAS, NRAS, BRAF, or MAPK1." (PMID 29872503, 2018). "In one study of 34 angiosarcomas, MAPK pathway alterations were identified in 53% of cases, including one tumor that was positive for a KRAS G12D mutation." (PMID 40012695, 2025). "53% of angiosarcomas displayed MAPK pathway activation, and harboured genetic activating mutations in KRAS, HRAS, NRAS, BRAF, MAPK1 or inactivating mutations in NF1 and PTPRB1." (PMID 29731980, 2018). "KRAS G12C mutation was present in eight patients overall – six patients in the STS cohort, one in the uterine sarcoma cohort (undifferentiated uterine sarcoma), and one in the breast sarcoma cohort (angiosarcoma)." (PMID 36741731, 2022).
brain arteriovenous malformations (12 papers, 2018 to 2026). "Somatic activating KRAS mutations in endothelial cells are the predominant cause of sporadic brain arteriovenous malformations (bAVMs) and also occur in sporadic extracranial AVMs." (PMID 41708990, 2026). "Mutation of KRAS in endothelial cells (KRAS-ECs) leads to intracerebral hemorrhage (ICH) in brain arteriovenous malformation (bAVM), resulting in severe disabilities or even death." (PMID 41642659, 2026). "Specific to sporadic VMs, missense mutations at codon 12 of the KRAS gene have been associated with arteriovenous malformations of the brain and with cutaneous sporadic VMs—mostly high-flow lesions." (PMID 35740480, 2022). "In sporadic brain arteriovenous malformations (AVMs) that are caused by KRAS mutations, using agents that inhibit the MAP-ERK pathway could also offer potential therapy for patients, at least in theory." (PMID 32066498, 2020). "We identified KRAS or BRAF mutations in 63% of the sporadic, intracranial AVM specimens we studied." (PMID 31891627, 2019).
colitis (12 papers, 2014 to 2025). Inflammation of the colon. "KRAS and BRAF mutations and CIMP-positive status were observed in 13% (2/16), 0% (0/16), and 19% (3/16) of invasive cancers in colitis-affected segments." (PMID 36827302, 2023). "The proportion of KRAS and BRAF mutations and CIMP-positive status in serrated polyps in colitis-affected segments tended to be higher in invasive cancer in colitis-affected segments in this study." (PMID 36827302, 2023).
metastatic melanoma (12 papers, 2017 to 2025). A melanoma that has spread from its primary site to another anatomic site. "The tolerability profiles in this phase I study have been seen in subsequent placebo-controlled, phase II trials of selumetinib plus dacarbazine in patients with treatment-naïve BRAF-mutant metastatic melanoma and selumetinib plus docetaxel in pretreated patients with KRAS-mutant advanced NSCLC." (PMID 28264648, 2017).
myeloid malignancies (12 papers, 2011 to 2024). "NRAS and KRAS activating point mutations are present in 10–30% of myeloid malignancies and are often associated with a proliferative phenotype." (PMID 38658558, 2024). "More generally, the RAS signalling pathway has been found to be fundamental in the development of myeloid malignancies, with somatic activating mutations in NRAS and KRAS genes estimated to be present in 20 to 40% of diagnosed cases of AML, CMML and JMML." (PMID 28637487, 2017). "The pathomechanism causing these symptoms in KRAS-mutant myeloid neoplasms was not fully elucidated." (PMID 32246016, 2020). "Our observations of RAS pathway co-alterations (CBL and KRAS) in the EPI6 signature aligns with the documented activation of this pathway in CUX1-altered MNs, as recently demonstrated in the context of 7q alterations in myeloid neoplasms." (PMID 38890297, 2024).
nasopharyngeal carcinoma (12 papers, 2009 to 2025). A carcinoma arising from the nasopharyngeal epithelium. "We discovered that nasopharyngeal carcinoma cells, which express a low level of KRAS and a high level of FTH1, are resistant to Erastin and RSL3." (PMID 36012290, 2022). "However, the qPCR analysis revealed that the mRNA expression of the KRAS gene in all ferroptosis-resistant nasopharyngeal carcinoma cells (CNE-2, S18, and S26) was much lower compared with tongue squamous cell carcinoma CAL33 and laryngeal squamous cell carcinoma (AMC-HN-8 and TU686)." (PMID 36012290, 2022). "However, all three nasopharyngeal carcinoma cells, including CNE-2, S18, and S26, expressed a very low mRNA level of KRAS compared with tongue squamous carcinoma and nasopharyngeal carcinoma cells." (PMID 36012290, 2022). "While the role of CDH4 in proliferation, cellular motility, invasion, and metastasis in a Rho GTPase-dependent manner has been described previously in the context of gastric and nasopharyngeal carcinoma, there are no reports linking CDH4 with oncogenic KRas signaling." (PMID 27894102, 2016).
serous cystadenoma (12 papers, 2016 to 2025). A serous neoplasm in which the cysts and papillae are lined by a single layer of cells without atypia, architectural complexity or invasion. "In this study, we successfully established a novel in vitro model of LGSOC from serous cystadenomas and developed carcinoma cell lines by introducing oncogenic KRAS and PIK3CA mutations." (PMID 35326657, 2022). "The acquisition of KRAS or BRAF and possibly other mutations including PAX-2 in OEIs and serous cystadenomas result in their gradual transformation to serous borderline tumors and ultimately LGSC." (PMID 30949203, 2019). "LGSC characterized by KRAS, BRAF, and ERBB2 gene mutations is thought to show stepwise progression and develop from serous cystadenomas and SBT." (PMID 29321056, 2018). "Four and five studies addressed KRAS and GNAS mutations between IPMN and serous cystadenoma (SCA) patients, respectively." (PMID 27512631, 2016). "The KRAS (OR 7.4 and 71.2) and GNAS (OR 30.2 and 15.3) mutations were more frequently found in IPMNs than in mucinous cystic neoplasms and in serous cystadenomas, respectively." (PMID 27512631, 2016). "In the OPN group, cfDNA positivity for KRAS mutation was detected only once, unexpectedly, in a patient with serous cystadenoma, for which alterations in this gene are not characteristic." (PMID 38255325, 2024). "Additionally, BRAF and KRAS mutations, which characterize serous borderline tumors (SBTs) and LGCSs, are absent in serous cystadenomas." (PMID 35326657, 2022). "We aimed to identify genetic variations in KRAS, BRAF, PIK3CA, and ERBB2 in LGSC/SBT/serous cystadenomas (SCAs) in a Japanese population." (PMID 31892193, 2019). "Serous cystadenomas do not have mutations in either KRAS or BRAF, whereas mucinous cystadenomas have KRAS mutations in up to 58%." (PMID 39758291, 2025). "KRAS and BRAF mutations are not found in the early serous cystadenoma stage, but they have been detected in the APSTs and adjacent cystadenoma epithelium in serous cystadenomas associated with small APSTs." (PMID 27128903, 2016).
urothelial carcinoma (12 papers, 2013 to 2026). A malignant neoplasm derived from the transitional epithelium of the urinary tract (urinary bladder, ureter, urethra, or renal pelvis). "Uromonitor® is a quantitative PCR-based assay targeting hotspot variants in the TERT promoter, FGFR3, and KRAS, which are frequently altered in urothelial carcinoma." (PMID 42193009, 2026). "The urothelial carcinomas harbored three private mutations with specific annotation, two KRAS mutations (p.Gly13Asp and p.Ala146Thr) with resistance level R1, and the level 4 NF1 p.Arg2637Ter." (PMID 35260767, 2022). "The urothelial carcinoma in this case harbored the wild-type form of KRAS, indicating its susceptibility to cetuximab." (PMID 27091477, 2016). "Based on these, KRAS mutations - similar to CRC but in contrast to urothelial carcinomas - seems to be frequent in UrC." (PMID 27283768, 2016). "In contrast to CRC, KRAS mutations are rare in urothelial carcinomas and primary bladder ADCs (~5% and ~10% respectively)." (PMID 27283768, 2016). "Additionally, a case of PRNRP with KRAS mutation was also reported synchronously with urothelial carcinoma with a distinct FGFR3/KDM6A mutation." (PMID 40860802, 2025). "On the one hand, KRAS and BRAF mutations occurred in UrC with similar frequencies as in CRC, in contrast to urothelial carcinoma, where both of these mutations are infrequent." (PMID 27283768, 2016). "Further analysis of the urothelial carcinoma of the urinary tract was carried out, and the results showed a wild-type KRAS gene in the urothelial carcinoma tissues." (PMID 27091477, 2016). "KRAS mutations have also been implicated in approximately 5% of urothelial carcinoma but is not considered a central part of its pathogenesis." (PMID 40860802, 2025). "Finally, we transfected urothelial carcinoma cells with KRAS and examined the expression of p16INK4a as well as markers of EMT." (PMID 23724131, 2013). "KRAS transfection of urothelial carcinoma cells led to upregulation of p16INK4a and uPA accompanied by loss of E-cadherin that could be inhibited by application of the kinase-inhibitor Sorafenib." (PMID 23724131, 2013).